BCL2 (BCL2 apoptosis regulator)
Diseases named in the same sentence as BCL2 in open-access papers (continued):
Sharing a sentence is not in itself a finding about the gene and the disease.
prostate carcinoma (continued). "The anti-apoptotic proteins, specifically BCL2, BCL2L1 (Bcl-xL), and MCL1, are often overexpressed in cancer and are associated with resistance and disease progression in prostate cancer." (PMID 40704654, 2025). "Preclinical models have shown that silencing Bcl-2 enhances apoptosis and suppress tumor growth, further underscoring its potential as a therapeutic target in advanced prostate cancer." (PMID 40841912, 2025). "In summary, this study demonstrates that downregulation of miR-143 contributes to abiraterone acetate resistance in prostate cancer by activating the p-JNK/p-Bcl2-Beclin1 signaling axis and promoting autophagy." (PMID 41446858, 2025). "Down-regulation of BCL-2 accelerates the apoptosis of prostate cancer cells, and exerts an anti-prostatic cancer effect." (PMID 40230723, 2025). "Understanding the nuances of AR signaling is critical, particularly regarding how the modulation of Cyclin D1 and Bcl-2 contributes to prostate cancer development and progression." (PMID 40008000, 2025). "Inhibition of cell death, particularly through the intrinsic apoptotic pathway governed by Bcl2 proteins, is a key factor in prostate cancer development and therapy resistance." (PMID 39554609, 2024). "Another in vitro study showed that it possessed significant anticancer activity against prostate cancer by inducing apoptosis and by down-regulating Bcl-2 protein." (PMID 39478959, 2024). "To investigate the role of HIST3H2A in regulating the proliferation of prostate cancer cells, we examined the expression of apoptosis-related proteins Caspase 9, Bax, and Bcl-2." (PMID 38684944, 2024). "Androgens have been shown to upregulate the expression of CXCR4, CXCR2, CXCR8, and, consequently, Bcl2 proteins through NF-κB-regulated transcription, increasing the metastatic capacity of prostate carcinoma cells." (PMID 39501277, 2024). "Combined treatment of docetaxel with CAPE inhibited the proliferation and survival of docetaxel-resistant prostate cancer cells via inhibiting Bcl-2 and c-Myc and induced metabolic interference and apoptosis." (PMID 39519572, 2024). "AKT1, mTOR, CASP9, and BCL2 were identified as the top targets involved in the anti-prostate cancer resistance effect of the SR-CR drug pair." (PMID 38326539, 2024). "Previously it has been reported that KLK10 promotes apoptosis of PC3 cells (one of the prostate cancer cells z via the down-regulation of Bcl-2)." (PMID 38707515, 2024). "Taken together, the reduction in HSP27, CFLIP, and CLU expression by doxazosin inhibits Bcl-2 function and thereby induces apoptosis in prostate cancer cells." (PMID 38535120, 2024). "In this study we identified BCL2 as a marker that classifies a subset of aggressive prostate cancers supporting the development of treatment approaches targeting apoptotic resistance pathways." (PMID 39286979, 2024). "The elevated Bcl2 mRNA and protein levels were specifically reported in the prostate cancer cell line (LNCaP)." (PMID 38438917, 2024). "Apigenin was reported to sensitize human CD44+ prostate cancer stem cells to cisplatin therapy by enhancing the cytotoxic and apoptotic effects of cisplatin through Bcl-2 regulation." (PMID 39519572, 2024). "Caspase-3, caspase-8, Bax, and Bcl-2 levels for compounds 4c, 4e, and staurosporine on prostatic cancer (PC-3) cell line." (PMID 38257358, 2024). "The inhibition of Hsp27 in DU145 and PC-3 prostate cancer cells not only reduced cell viability but also induced apoptosis by decreasing Bcl-2 levels and increasing Bax levels." (PMID 38535120, 2024). "In this research, HLT-101 induced apoptosis in prostate cancer cells by downregulating the expression of BCL-2, an apoptosis inhibitor, and up-regulating BAX, a pro-apoptotic factor." (PMID 37994101, 2024). "The data presented here confirmed that PTX in combination with SFN additively reduced the level of Bcl2 protein compared with PTX or SFN alone in both prostate cancer cell models (PC-3 and LNCaP)." (PMID 38438917, 2024).
prostate carcinoma (continued). "In vitro studies demonstrated that formononetin inhibited the proliferation and induced apoptosis of prostate cancer cell PC-3 through the induction of Bax/Bcl-2 ratio and regulation of p38/Akt pathway." (PMID 38874510, 2024). "One of the strategies that a cancer cell adopts to evade apoptosis is to upregulate the expression of survival signaling proteins, such as Bcl2, which showed higher levels in prostate cancer." (PMID 38438917, 2024). "Bcl-2 and Bax are two proteins that are centrally involved in the regulation of apoptosis, and their roles are particularly important in the context of prostate cancer." (PMID 38535120, 2024). "Nevertheless, in PC3 prostate cancer cells, mangiferin substantially boosts the expression of miR‐182, while enormously eliminating Bcl‐2‐expression, and stimulates caspase‐3 activity and apoptosis." (PMID 39479608, 2024). "The low amount of Bcl-2 protein in the prostate cancer cells was insufficient to counteract the strong pro-apoptotic signal induced by cisplatin treatment." (PMID 39501277, 2024). "Following atorvastatin therapy, PC3 human prostate cancer cells’ ability to proliferate is inhibited, as a result of downregulating Bcl‐2 and upregulating miR‐182." (PMID 39479608, 2024). "Selenium nanoparticles have also been found to upregulate miR-16, which reduces the expression of cyclin D1 and BCL-2, leading to enhanced apoptosis induction in prostate cancer cells." (PMID 37765058, 2023). "↓ Tumor cell growth, ↑ apoptosis, ↓ metastatic spread by α6 integrin, ↑ Bax, and ↓ Bcl-2 protein in prostate cancer cells (DU145 and LNCaP)." (PMID 37762572, 2023). "This study demonstrated that CBD inhibits prostate cancer cells’ activation of Bcl2 signalling transduction pathways in this study." (PMID 36853473, 2023). "Androgen-independent prostate cancer cells often overexpress the anti-apoptotic protein B-cell lymphoma 2 (BCL2), while retinoids can induce apoptosis and influence growth factor-beta in prostate cancer models." (PMID 37762648, 2023). "Bcl-2 inhibits apoptosis of the prostate cancer cells subjected to androgen deprivation, allowing the cancerous cells to survive without the required hormone." (PMID 36826044, 2023). "Thus, it is reasonable to believe that the decrease in Bcl-2 levels caused by Smp43 might co-exist with the increase in Beclin 1, which is consistent with the antitumor mechanism of licorice and licochalcone-A against human LNCaP prostate cancer cells." (PMID 37235381, 2023). "It was reported that MSAs (e.g., paclitaxel) treatment can induce phosphorylation of Bcl-2 in prostate cancer cells and other cancer cells that express Bcl-2, leading to cell apoptosis." (PMID 37444418, 2023). "For example, transfection with the PTEN gene, which negatively regulates Bcl-2, potentiated the effects of radiation therapy on several prostate cancer cell lines (PC-3-Neo, PC-3-Bcl-2, and LNCaP)." (PMID 38026933, 2023). "Levels of anti-apoptotic proteins Bcl-2, Bcl-xL, and Mcl-1 are upregulated in prostate cancer and contribute to prostate cancer progression." (PMID 37173959, 2023). "Prostate cancers containing the overexpression of BCL2 have been noted as being a biomarker for PARP sensitivity as well." (PMID 37508568, 2023). "In conclusion, this study demonstrated that Curcusone C can target PCBP2 protein, thereby affecting TGF/Smad signaling pathway and Bax/Bcl-2 balance, and ultimately exert anti-prostate cancer activity." (PMID 37814239, 2023). "On the contrary, the gene expression of anti-apoptotic protein BCL2 was significantly reduced, indicating that FA has apoptotic activity on prostate cancer cells." (PMID 35594510, 2022). "NF-kB inhibits cell death and promotes cell proliferation in prostate cancer by the overexpression of Bcl-2." (PMID 36232606, 2022).
prostate carcinoma (continued). "The western blot analysis showed that cirsilineol suppressed the expression of Bax and upregulated the expression of Bcl-2 in prostate cancer DU-145 cells." (PMID 35855832, 2022). "Their study also reported increased Bax and decreased Bcl-2 levels after treatment in prostate cancer cells." (PMID 35742944, 2022). "This compound triggers apoptosis in human prostate cancer LNCaP and PC-3 cell lines by downregulation of BCL2 and BCL2L1." (PMID 36497321, 2022). "PKCα activation also increases anticancer drug resistance in prostate cancer cells by increasing Ser70-phosphorylated Bcl-2 and total Bcl-2 protein." (PMID 36358843, 2022). "qRT-PCR was used to detect the changes of apoptosis related genes caspase-3, PARP, Bax and Bcl-2 in prostate cancer cell DU145 and PC-3 after the effect of silencing Hsp27 and ATL-1 treated." (PMID 36686743, 2022). "Inducing apoptosis through Bcl-2-dependent and independent pathways at dosages lower than the individual agents suggest the relevance of this combination for Bcl-2-resistant prostate cancers." (PMID 36362950, 2022). "This indicates that SIRT6 promotes the survival and proliferation of prostate cancer by increasing Bcl-2 expression and preventing cell cycle arrest." (PMID 36291902, 2022). "Largely, HSP has limited activities on preventing prostate cancer treatment, where it can induce caspase and Bax/Bcl2 mediated apoptosis and regulate some inflammatory markers." (PMID 35128104, 2022). "Quantitative real-time PCR assay was performed to detect the mRNA expression of lncRNA MIAT, miR-361-3p, CCAR2, Bax, and Bcl-2 in the prostate cancer tissues or cells." (PMID 36245704, 2022). "TRAIL-induced cytochrome c release has been seen to increase in acute acidic pHe compared to normal pHe in prostate carcinoma, while multiple anti-apoptotic proteins (cFLIP, cIAP1, cIAP2, and Bcl-2) remained overall unchanged." (PMID 35281089, 2022). "miR-34a indicates the chemosensitization effect of paclitaxel on prostate cancer cells by targeting Bcl-2 protein." (PMID 34863188, 2021). "miRNAs abnormally overexpress Bcl-2 in multiple malignancies, including prostate cancer, osteosarcoma cancer, and breast cancer." (PMID 35116035, 2021). "Earlier immunohistochemical studies reported increased levels of BCL2 protein in prostates of castrated patients and in advanced prostate cancer." (PMID 33668112, 2021). "As with other solid malignancies, BCL-XL and MCL-1 appear to be more important than BCL-2 for cell survival in prostate cancer, although it is likely there is significant inter- and intra-patient heterogeneity." (PMID 35008216, 2021). "Published in 1996, Krajewska and colleagues were the first to undertake a comprehensive immunohistochemical analysis of the three major anti-apoptotic BCL-2 proteins in prostate cancer." (PMID 35008216, 2021). "The pan-BCL-2 inhibitor AT-101 was evaluated in early phase clinical trials for prostate cancer, but off-target gastrointestinal toxicities were dose limiting, and there was no significant anti-cancer activity." (PMID 35008216, 2021). "In fact, prior to the development of BH3 mimetics with high specificity, ‘pan-BH3 mimetics’ with broad engagement of multiple anti-apoptotic BCL-2 proteins were evaluated in pre-clinical studies, with promising results, including in prostate cancer." (PMID 35008216, 2021).
prostate carcinoma (continued). "A number of immunohistological studies have shown high levels of MCL-1 and BCL-XL in prostate cancer, but BCL-2 appears to be expressed at lower levels, with more interstudy variability." (PMID 35008216, 2021). "Bcl-2 also promotes the transformation of prostate cancer cells from an androgen-dependent to an androgen-independent growth stage." (PMID 34170852, 2021). "Mackey concluded in some experiments that the higher Bcl-2-to-Bax ratio results in the higher the chance of radiotherapy failure in prostate cancer patients." (PMID 34528498, 2021). "This will be important in determining the clinical translatability of targeting these proteins in advanced prostate cancer, although, as discussed, changes in BCL-2 proteins are dynamic, and this cannot be evaluated with immunohistochemical studies." (PMID 35008216, 2021). "By targeting Bcl-2 in prostate cancer cells, Yao Shi discovered that MEG3 played a critical role in controlling cell proliferation, apoptosis, and migration." (PMID 34421993, 2021). "For example, enhanced expression of BCL-2 is associated with the development of androgen-refractory prostate cancer, whilst in CLL, higher expression of BCL-2 is an adverse prognostic feature." (PMID 33799592, 2021). "Induced apoptosis in prostate cancer cells by down-regulating Bcl-2 through ROS-dependent ubiquitin-proteasomal degradation pathway." (PMID 34026649, 2021). "Application of lycopene to hormone-refractory prostate cancer cell lines in a dose-dependent manner has resulted in a decrease of Bcl-2 expression, an increase in Bax proteins, and induction of apoptosis by causing cycle distribution changes." (PMID 32718121, 2021). "Decreased BCL2 mRNA levels and increased BCL2 promoter methylation was reported in prostate cancer compared to adjacent normal tissue." (PMID 33668112, 2021). "Previous studies confirmed that miR-204-5p promotes apoptosis by targeting BCL2 in prostate cancer cells, validating its tumor-suppressive role." (PMID 34512726, 2021). "In human prostate cancer, morusin inactivated STAT3 signaling and caused apoptosis by inhibiting Bcl-2, Bcl-xL and surviving." (PMID 34768743, 2021). "With regard to this synergy, in PC-3—the cell lines of human prostate cancer—quercetin and 2-methoxyestradiol display antiproliferative and proapoptotic activity by growing the Stage G2/M of the cell population and decreasing Bcl-2/Bax." (PMID 33807174, 2021). "Similar reports suggest that miRNA-204-5p promotes apoptosis in prostate cancer cells by targeting Bcl2." (PMID 34723710, 2021). "It was previously reported that the activation of the JNK signaling pathway is sufficient to phosphorylate Bcl-2 at both residues Ser70 and Thr56, thereby inducing apoptosis in prostate cancer in vitro." (PMID 34391437, 2021). "In summary, immunohistochemical evidence suggests that BCL-2 proteins play an important role in prostate cancer progression as the tumor becomes more resistant to cell death stimuli." (PMID 35008216, 2021). "Established therapies for prostate cancer enact their therapeutic activity, to some extent, by the induction of apoptosis, and several studies have suggested that BCL-2 proteins play an important role in therapeutic resistance." (PMID 35008216, 2021). "Bcl-2 is an important oncotarget in prostate cancer and miRNAs are a class of therapeutics commonly exploited to downregulate Bcl-2." (PMID 34170852, 2021).
prostate carcinoma (continued). "Knockdown of BMI1 in docetaxel resistant prostate cancer cells inhibited the expression of cyclin D1 or BCL2, the downstream targets of the Wnt/β–catenin pathway." (PMID 32726929, 2020). "Its combination with ABT-737, which inhibits Bcl-2, Bcl-xl, and Bcl-w, led to an induction of the intrinsic apoptotic pathway and to a synergistic cytotoxicity in prostate cancer cells and 3D spheroids." (PMID 32580291, 2020). "With its pro-survival function, Bcl-2 is indispensable in the transition of prostate cancer cells from androgen-dependence to androgen-independence and correlates with the androgen-independent phenotype 28." (PMID 32685011, 2020). "The treatments with statins and zoledronic acid also significantly reduced the expression of the anti-apoptotic genes Bcl-2 and Svv, even in chemo-resistant A2780cis cells, which is in line with studies in breast, colorectal, and prostate cancer." (PMID 32727400, 2020). "Other “in vitro” studies demonstrated that Bcl-2 overexpression confers resistance to hormonal therapy among prostate cancer patients." (PMID 32341393, 2020). "For example, miR‐1266‐5p is down‐regulated in prostate cancer, which regulates the apoptotic pathway by targeting the antiapoptotic genes BCL2 and BCL2L1." (PMID 32961635, 2020). "Our findings suggest that use of one or more currently available agents targeting the TGF-β/acetylated KLF5/BCL2 signaling axis is beneficial to patients with DTX-resistant prostate cancer." (PMID 32685011, 2020). "Overexpression of Bcl-2 correlates with the progression and metastasis of prostate cancer and was shown to inhibit anoikis at least in intestinal epithelial cells." (PMID 32033410, 2020). "A small-molecule inhibitor of Bcl-2, (-)-gossypol, triggered autophagic cell death and inhibited the growth of androgen-independent prostate cancer xenografts with high levels of Bcl-2 to resist apoptosis." (PMID 33239065, 2020). "Another study using a prostate carcinoma line demonstrated that NCAD-catenin adhesion complex results in up-regulation of the anti-apoptotic protein Bcl-2, whereas the level of the proapoptotic protein Bax remained constant." (PMID 32967889, 2020). "Ratio of Bax / Bcl-2 in favor of cell apoptosis is improved in prostate cancer cells by the means of apigenin (10 μM)." (PMID 33195038, 2020). "For the protein-ligand interaction studies, we have selected the specific target proteins which are involved in lipogenesis and apoptosis pathway including FASN and Bcl-2 because prostate cancer survival depends on the lipogenesis pathway." (PMID 32258129, 2020). "For example, miR-101 suppresses cell proliferation and facilitates cell apoptosis by inhibiting mTOR in Saos-2 cells, promotes Bcl2-regulated apoptosis by RLIP76 in prostate cancer cells, represses tumour growth and migration by ROCK1 in osteosarcoma cells." (PMID 33072314, 2020). "MiR-101 overexpression disrupts the PI3K-AKT pathway and promotes Bcl2-regulated apoptosis induced by RLIP76 in prostate cancer cells." (PMID 33072314, 2020). "In a prostate cancer tissue microarray, we performed immunohistochemistry staining of Bcl-2 and acetylated KLF5." (PMID 32685011, 2020). "The PI3K/AKT pathway has been previously reported to induce Bcl-2 and inhibit apoptosis in human prostate cancers." (PMID 31317026, 2019).